STAT3 (signal transducer and activator of transcription 3)
Diseases named in the same sentence as STAT3 in open-access papers (continued):
Sharing a sentence is not in itself a finding about the gene and the disease.
prostate carcinoma (continued). "Previous studies showed that BaP affected the JAK2/STAT3 pathway by activating AhR to promote prostate cancer progression." (PMID 38410974, 2024). "STAT3 is a primary downstream regulator of IL-6 expression with its distinctive role in adaptable proliferation and neoplastic transformation in prostate cancer." (PMID 39574470, 2024). "Addition of STAT3 inhibitor to paclitaxel therapy resulted in significant mitigation of chemotherapy resistance in mouse model of prostate cancer and prolonged survival of animals." (PMID 38794298, 2024). "The STAT3 pathway can induce the cellular senescence of prostate cancer cells and thus inhibit cancer metastasis." (PMID 39161800, 2024). "The anti-cancer properties of lutein (3,4,2′,4′-tetrahydroxychalcone) against various carcinomas involve the suppression of STAT3 activation in head and neck cancer, liver cancer, malignant pleural mesothelioma, myeloma, and prostate cancer." (PMID 38686052, 2024). "Our collective research has also shown that CFF-1 exerts potent anti-tumor immunity, effectively hindering tumor growth and metastasis in prostate cancer via the EGFR/JAK1/STAT3 pathway, subsequently inhibiting PD-1/PD-L1 checkpoint signaling." (PMID 38484140, 2024). "Some of the genes that have been linked to the development of prostate cancer are PIK3R1, SRC, STAT3, HSP90AA1, AKT1, MAPK1, SESR1, and AR." (PMID 39114070, 2024). "In the DU145 human prostate cancer cell line, Silibinin decreased activated STAT3 in a dose-dependent manner." (PMID 38339245, 2024). "Among various causes of prostate cancer androgen receptor (AR) signaling, PTEN/PI3K/AKT/mTOR pathway, IL6/STAT3 and STAT5a/b are the most common pathways involved in prostate cancer cell survival and resistance." (PMID 36648960, 2023). "IGFBP2 also promotes STAT3 activity in prostate cancer invasion and promotes NF-κB-driven invasion in pancreatic cancer." (PMID 37029430, 2023). "PGG inhibited STAT3 Tyr705 phosphorylation in the prostate cancer DU145 cell line, thereby downregulating STAT3 transcriptional targets, such as Bcl-XL and Mcl-1, which decreased cell viability and increased caspase-mediated apoptosis." (PMID 37375411, 2023). "The following terms were combined in our search: prostate cancer; biomarkers; IL-17; STAT3; NRP1; LIMK1; Cofilin-1; PSMA; AMACR; CD15; Appl1; Sortilin; Syndecan-1, and p63." (PMID 37371647, 2023). "In human prostate carcinoma cells, GlcN supplementation inhibits STAT3 signaling and prevents the expression of the STAT3 target survivin, an apoptosis inhibitor." (PMID 37107691, 2023). "Il-6 is a pleiotropic cytokine that in this context, also promotes prostate cancer growth by activating STAT3 signaling." (PMID 36900168, 2023). "One study found that STAT3 is a direct target that is bound by acacetin in DU145 prostate cancer cells." (PMID 37266143, 2023). "In line with our results, it was recently reported that pharmacological disruption of EED function inhibited STAT3 activation in prostate cancer cells." (PMID 36923952, 2023). "High-fat diets can induce localized inflammation in the prostate gland, promoting prostate cancer growth by suppressing the tumor immune response, potentially through the IL-6 and STAT3 signaling pathway." (PMID 38140390, 2023). "In pancreatic, colorectal and prostate cancer, high expression of IL6/JAK/STAT3 pathway proteins associates with poor clinical outcomes." (PMID 37199043, 2023). "Sulforaphane has been shown to have antioxidant, anti-inflammatory, and anticancer properties, through the activity of phenethyl isothiocyanate, inhibiting the Signal Transducer and Activator of Transcription 3 (STAT3) activation in prostate cancer cells." (PMID 37836558, 2023). "Excessive activation of STAT3 and STAT5 are implicated in numerous hematopoietic and solid malignancies, including chronic and acute myeloid leukemia, melanoma, and prostate cancer." (PMID 38127921, 2023).
prostate carcinoma (continued). "Huang reported that TAMs produce CCL5, which activates the I-CATENIN/STAT3 pathway, potentially contributing to prostate cancer stem cell survival and metastasis." (PMID 36825082, 2023). "Instead, by targeting the STAT3 signaling pathway, pimozide was found to inhibit proliferation and promote apoptosis in prostate cancer cells." (PMID 36983018, 2023). "We demonstrated the efficacy of ZQD treatment in reducing prostate cancer cells proliferation and tumor growth, evidenced by inhibiting the activation of IL-6/STAT3 signaling pathway in vitro (PC3 and DU145 cells) and xenograft tumor model in vivo." (PMID 37576403, 2023). "The overexpression of IL-6 increases the resistance of prostate cancer cells mainly through the JAK/STAT3 axis." (PMID 36982155, 2023). "STAT3 has been shown to increase cell proliferation and cell cycle in prostate cancer, hence promoting cell survival." (PMID 36852795, 2023). "Overexpression of active STAT3 in prostate cancer cells induces resistance to enzalutamide treatment." (PMID 37576403, 2023). "DU145 and LN-17 prostate cancer cell lines treated with STAT3 siRNA were characterized by decreased proliferation compared with cells treated with control siRNA." (PMID 38067351, 2023). "We demonstrated that ZQD regulated the IL6/STAT3 signaling pathway on the tumor microenvironment and thus inhibits the proliferation of prostate cancer cells." (PMID 37576403, 2023). "Upregulation of STAT3 leads to a decrease in the sensitivity of prostate cancer cells to enzalutamide." (PMID 37576403, 2023). "LDL leads to increased phosphorylation of STAT3 protein in prostate cancer cells and upregulates the levels of oncogenes controlled by this transcription factor." (PMID 37953784, 2023). "GRIM-19-Si-Stat3 inhibited tumor growth and increased the apoptosis of cancer cells in vivo in a prostate cancer xenograft model." (PMID 38067351, 2023). "LncRNAs are able to regulate the proliferation and metastasis of prostate cancer cells and are related to the regulation of the STAT3, NF-κB, PTEN, PI3K/Akt and miRNAs pathways." (PMID 37297021, 2023). "Interleukin 6 (IL-6) is an anti-inflammatory myokine that has been found to activate AR-mediated gene expression via a signal transducer and activator of transcription 3 (Stat3) activator pathway in prostate carcinoma cells." (PMID 38139289, 2023). "It was further demonstrated that heat shock protein 27 increased the metastatic and invasive ability of prostate cancer cells by upregulating the phosphorylation level of STAT3 in prostate cancer cells, which led to epithelial mesenchymal transition." (PMID 37576403, 2023). "JMJD1C also reportedly demethylates STAT3 to restrain plasma cell differentiation and rheumatoid arthritis to participate in the progression of prostate cancer via an upregulation of TNF-α and mediate myocardial hypertrophy via angiotensin II (Ang II)." (PMID 37759870, 2023). "Prostate cancer cells become resistant to enzalutamide by producing IL-6, which leads to the activation of STAT3." (PMID 37576403, 2023). "A previous study found that acacetin functions as a STAT3 inhibitor by directly binding to the STAT3 protein in prostate cancer cells." (PMID 37266143, 2023). "Although few studies on MAOA in stromal cells have been performed, it was suggested that the expression of MAOA is increased in stromal fibroblasts of prostate cancer and that this promotes tumor cell growth through the IL-6/STAT3 signaling pathway." (PMID 37509535, 2023). "miR-424-5p targeted E3 ligase COP1 to stabilize STAT3, thus promoting cell proliferation of prostate cancer cells." (PMID 34976194, 2022). "In line with this, activation of STAT3, the downstream mediator of IL-6 signal transduction, was elevated by coculture of prostate cancer cells with bone marrow stromal cells, and subsequently reduced following IL-6 blockade." (PMID 35213227, 2022).
prostate carcinoma (continued). "The knockdown of STAT3 in MDSCs derived from patients with prostate cancer reduced the immunosuppressive functions of MDSCs against effector T cells by STAT3." (PMID 36010693, 2022). "Scoparone inhibited the transcriptional activity of STAT3 and thus suppressed the transcription of oncogenic STAT3 target genes, leading to inhibition of the growth of prostate cancer cells." (PMID 36613654, 2022). "Study results showed that garcinol inhibited both total and phosphorylated STAT3 in breast, pancreatic, and prostate cancer cell lines and reduced cell invasion in these cancer cell lines in a dose-dependent manner." (PMID 36193062, 2022). "We have previously demonstrated a growth inhibitory effect of the small molecule STAT3 inhibitor galiellalactone as monotherapy in various prostate cancer models where STAT3 is constitutively activated in the tumor cells." (PMID 35917644, 2022). "ASC-J9, a curcumin analog named dimethylcurcumin, suppresses proliferation and invasion in prostate cancer by inhibiting the phosphorylation of STAT3 (pSTAT3)." (PMID 35628356, 2022). "While the activation of STAT3 is usually transient under normal conditions, STAT3 activation tends to become more persistent in a number of hematopoietic malignancies, such as multiple myeloma, melanoma, ovarian cancer, as well as prostate cancer." (PMID 35700456, 2022). "Combination of TIGIT checkpoint inhibitor with blockage of IL-6R and STAT3 enhanced cytotoxicity of NK92 cells towards prostate cancer cells." (PMID 35865518, 2022). "Collectively, these results showed that QL serum resensitized paclitaxel-resistant prostate cancer cells to paclitaxel via IL-6/STAT3 signaling in TAMs." (PMID 35193986, 2022). "The augmented expression of IL-11R and the activation of STAT3 have been observed in human prostate cancer, indicating IL-11R as a promising therapeutic target against human androgen-resistant and advanced prostate cancer." (PMID 36010693, 2022). "The findings added new sights into understanding the regulation of STAT3 signaling in prostate cancer." (PMID 34976194, 2022). "This compound inhibits the activation of src and JAK kinases by suppressing the phosphorylation, preventing the STAT3 activation in prostate cancer cells." (PMID 36496432, 2022). "In correspondence with the identified mechanism, the efferocytosis of apoptotic prostate cancer cells induced a more robust activation of STAT3 and MIF expression compared to the efferocytosis of apoptotic normal cells." (PMID 36496973, 2022). "ASC-J9 is known for suppressing the invasion of prostate cancer cells by inhibiting STAT3 phosphorylation." (PMID 35628356, 2022). "STAT3 signaling was one of the well-characterized cancer driver pathways in prostate cancer, which was critical for maintaining uncontrolled cell proliferation." (PMID 34976194, 2022). "Our study found that cell models of advanced prostate cancer demonstrated constitutive expression of STAT-3, and also exhibited characteristics such as a high secretion of growth factors, such as VEGF and cytokines, such as IL-6 and CXCL8." (PMID 35465350, 2022). "Signal Transducer and Activator of Transcription 3 (STAT3) is known to be involved in castration-resistant prostate cancer and to interact with androgen receptor (AR)-signaling." (PMID 35917644, 2022). "As we showed in our findings, MAGI2-AS3 promoted prostate cancer cell apoptosis, and repressed the activity of STAT3 signaling." (PMID 34976194, 2022). "The marine natural product heteronemin exhibits potent antitumor effects by inhibiting c-Met/STAT3 activation in HGF-stimulated refractory prostate cancer cells." (PMID 35705962, 2022). "Herein, Pinus mugo EO (PMEO) is identified as an inhibitor of constitutive STAT3 phosphorylation in human prostate cancer cells, DU145." (PMID 35956786, 2022).
prostate carcinoma (continued). "The aberrant expression of lncRNAs in prostate cancer has been well-documented and progression rate of tumor cells are regulated via affecting STAT3, NF-κB, Wnt, PI3K/Akt and PTEN, among other molecular pathways." (PMID 35773731, 2022). "In this work, we present data demonstrating the anti-STAT3 activity and consequent cytotoxic effects of a panel of EOs in human prostate cancer cells characterized by constitutive STAT3 activation." (PMID 35956786, 2022). "The AKT and STAT3 pathways are closely related to the polarization process of macrophages, and our data further confirmed that prostate cancer cells can activate the AKT and STAT3 pathways through exosomes to cultivate M2 macrophages." (PMID 35941539, 2022). "Our data also showed that COP1 was upregulated and STAT3 was downregulated in prostate cancer cells with overexpression of MAGI2-AS3, moreover, the effects of MAGI2-AS3 on COP1 was reversed by miR-424-5p mimic." (PMID 34976194, 2022). "The aim of this study was to investigate if a combination of enzalutamide and the small molecule STAT3 inhibitor GPB730 can enhance the therapeutic effect of enzalutamide in advanced prostate cancer." (PMID 35917644, 2022). "In this study, we first evaluated the anti-STAT3 activity of a panel of EOs in the human prostate cancer cell line DU145, which constitutively expresses active STAT3." (PMID 35956786, 2022). "In conclusion, the current data suggested that MAGI2-AS3 acted as a sponge for miR-424-5p to elevate COP1 expression and inactivated STAT3 signaling in prostate cancer cells." (PMID 34976194, 2022). "A recent experiment has shown how lncRNAs can regulate LIF/STAT3 axis in affecting immune response of prostate cancer cells." (PMID 35773731, 2022). "Tyr705 phosphorylation, which is vital for STAT3 dimerization and is prevalent in prostate cancer, was demonstrated to be downregulated by both compounds, followed by reduced STAT3 transcriptional activity." (PMID 35712699, 2022). "Heteronemin efficiently inhibited the HGF-stimulated c-Met/STAT3 in prostate cancer cells and also suppressed HGF-induced colony formation." (PMID 35705962, 2022). "In contrast, the silencing of androgen receptor expression enhances CSC-like traits in prostate cancer via IL-6/STAT3 signaling." (PMID 36010693, 2022). "In their study, they demonstrated that HO-1 and STAT3 bind to each other and therefore inhibit the phosphorylation of STAT3 and subsequent nuclear translocation of pSTAT3 in prostate cancer cells." (PMID 35326116, 2022). "This highlights the feasibility of generating a therapy directed against the IL6R/STAT-3 axis in advanced stages of prostate cancer with these characteristics." (PMID 35465350, 2022). "In prostate cancer, it was observed that STAT3 activation induces stem cell-like phenotypes due to regression of androgen receptor expression." (PMID 36359888, 2022). "The activation of LIF/LIFR axis stimulates JAK1/STAT3 signaling to preserve PD-L1 expression, leading to immune evasion of prostate cancer." (PMID 35773731, 2022). "Several studies have demonstrated that PGG can inhibit STAT3 phosphorylation and suppress tumor growth and metastasis in breast and prostate cancer cells." (PMID 35890129, 2022). "The enhancer of zeste homolog 2/STAT3 signaling is demonstrated to play a promoting role in chemoresistance and chemo‐related adverse events in prostate cancer treatment." (PMID 35356799, 2022). "It seems that STAT3 is a negative regulator of autophagy in prostate cancer cells upon docetaxel chemotherapy." (PMID 35317831, 2022). "MiR-375 directly interfered with the expression of PTPN4, which in turn stabilized phosphorylated STAT3 in castration-resistant prostate cancer." (PMID 36556168, 2022). "ADAM12 was also reported as a novel regulator in tumor angiogenesis via STAT3 signaling and as a prognostic marker for various cancers, including breast and prostate cancers." (PMID 34121340, 2021).
prostate carcinoma (continued). "Elevated levels of IL-6 are observed in a large number of patients with solid tumors including prostate cancer, and IL6 stimulates the activation of STAT3 signaling pathway, which is often associated with poor patient outcomes." (PMID 34684783, 2021). "Consistently, the activity of the IL-6/STAT3 signaling pathway is proportional to the growth rate of advanced prostate cancer." (PMID 33535458, 2021). "In prostate cancer cells the overexpression of IL-8 induced proliferation, invasion and decreased apoptosis via STAT-3/AKT/NF-kB by increasing phosphorylation of STAT3, AKT and NF-kBp65." (PMID 35011682, 2021). "β-Caryophyllene suppresses STAT3 activation in human breast and prostate carcinoma and in multiple myeloma cell lines via the inactivation of IL-6." (PMID 34205739, 2021). "Increased STAT3 activity is observed in more than 50% of malignancies, including breast, ovarian, lung, prostate cancer, leukemia, and lymphoma." (PMID 34769241, 2021). "On the other hand, the enhancer of zeste homolog 2 (EZH2) component of the polycomb 2 complex determines K180 tri-methylation, which is essential for maintaining STAT3 phosphorylation and transcriptional activity in glioblastoma and prostate cancer cells." (PMID 34642818, 2021). "All the evidence showed that LINC00467 regulated STAT3 to promote the progression of prostate cancer by sponging miR-494-3p." (PMID 34094954, 2021). "HDAC1, on the other hand, is involved in the deacetylation process, resulting in the inhibition of STAT3 transcriptional activity in human prostate cancer (PC3) cell lines." (PMID 34769241, 2021). "Recently, a potential role of SHMT2 has been proposed as a modulator of STAT3, a master regulator of energy metabolism, which is involved in the transition of prostate cancer towards a more aggressive phenotype." (PMID 33917317, 2021). "GK mediates the dephosphorylation of STAT3 in Tyr705 and prevents it from entering the nucleus, thereby inhibiting STAT3-mediated gene expression, such as antiapoptotic Bcl-XL protein, thereby inhibiting the proliferation of prostate cancer DU-145 cells." (PMID 34539403, 2021). "A prostate cancer cell line study revealed that piperine decreased the expression of phosphorylated STAT-3 and nuclear factor-κB (NF-κB)." (PMID 33921897, 2021). "The disruption of STAT3 signaling in PTEN null prostate cancer cells can promote tumor growth in mice." (PMID 34067832, 2021). "Over time, however, MSCs eventually select for prostate cancer cells that are refractory to IL-28 induced apoptosis and have increased STAT3 signaling." (PMID 33526787, 2021). "STAT3 is elevated in prostate cancer cells as well as in many types of tumor-infiltrating immune cells, therefore pharmacological approaches aim to downregulate STAT3 function." (PMID 34067832, 2021). "In conclusion, STAT3 inhibition by GPB730 enhances the antitumoral activity of anti-CTLA-4 in a prostate cancer mouse model, possibly by blocking STAT3 mediated resistance mechanisms such as Tregs in the immunosuppressive environment." (PMID 33786638, 2021). "Most studies were focused on the expression and phosphorylation of STAT-3 in various prostate cancer models." (PMID 34204596, 2021). "STAT3 participates in the pathogenesis of various malignancies, including melanoma, prostate cancer and colonic cancer." (PMID 34224294, 2021). "By physically interacting with IGF-1R, SDCBP activates STAT3 and thus regulates prostate cancer pathogenesis." (PMID 34445387, 2021). "Ginkgetin blocks its entry into the nucleus, which in turn inhibits STAT3-mediated gene expression, thus inhibits the proliferation of DU-145 prostate cancer cells." (PMID 34539403, 2021). "On the other hand, overexpression of constitutively active STAT-3 in prostate cancer cells contributes to enzalutamide resistance." (PMID 34204596, 2021).